ROBO1 (roundabout guidance receptor 1)
Diseases named in the same sentence as ROBO1 in open-access papers (continued):
Sharing a sentence is not in itself a finding about the gene and the disease.
tumor (continued). "Meanwhile, Robo1, one of several Slit receptors, is upregulated in response to the decrease in miR-218, which in turn induced a reactive upregulation of the Slit-Robo1 pathway through an interaction with Slit2, thus facilitating tumor cell migration and invasion." (PMID 20300657, 2010). "Thus, upregulation of Robo1 in response to the decrease in miR-218 induced a reactive upregulation of the Slit-Robo1 pathway through its interaction with Slit2, thus facilitating tumor cell invasion and metastasis." (PMID 20300657, 2010). "Robo1 was found at the membrane of Src transformed cells where it may act as a functional receptor to promote tumor cell migration and invasion." (PMID 21301049, 2010). "The roles of ROBO1 in tumor development and progression remain unclear." (PMID 36459288, 2023). "The results demonstrated that ROBO1-FL-expressing tumour cells showed increased proliferation and colony formation ability in the presence of recombinant SLIT2 (rSLIT2), and this advantage could be abolished by sROBO, a soluble peptide containing the first 2 Ig domains as a ligand-binding trap." (PMID 36792623, 2023). "Taken together, these results indicated that ROBO1 may serve as a tumor suppressor in CCA progression, and ROBO1E280* is a loss-of-function mutation, interrupting the SLIT2/ROBO1 signaling pathway and reversing the tumor-suppressing effects of wild-type ROBO1." (PMID 35615148, 2022). "Besides this, the SLIT2/ROBO1 pathway seems to play contradictory roles in tumor progression." (PMID 35615148, 2022). "We hypothesized that Slit2/Robo1 signaling might be involved in the tumor development of CRC." (PMID 31242633, 2019). "Thus, Slit2/Robo1 signaling plays a tumor-promoting role during the intestinal tumorigenesis." (PMID 25605242, 2015). "Therefore, the injection of 90Y-anti-ROBO1 in combination with a radiosensitiser to small tumours may deliver more effective antitumour activity." (PMID 25006547, 2014). "We used 111In-anti-ROBO1 as a biodistribution surrogate to predict in vivo behaviours of 90Y-anti-ROBO1, because previous reports indicate that 111In- and 90Y-labelled antibodies, proteins, and peptides are biologically equivalent with respect to their uptake in tumours and other major organs." (PMID 25006547, 2014). "Therefore, inhibitors of Src, Abl, Robo1 and small GTPases may target a coordinated pathway required for tumor cell migration." (PMID 21301049, 2010). "Therefore, if Slit2 were promoting tumor cell migration, Src may also be expected to increase Robo1 expression in transformed cells." (PMID 21301049, 2010). "Studies in mouse models showed that ROBO-1-targeted CAR-NK cells, combined with brachytherapy, significantly reduced tumor volume." (PMID 40260240, 2025). "ROBO1, a member of the ROBO family, plays key roles in axon guidance receptor regulation and has been reported to mediate tumor angiogenesis." (PMID 39114443, 2024). "Overexpression of SLIT2 and deletion of ROBO1 in SCLC cells have shown the anti-tumor and pro-tumor effects of SLIT2 and ROBO1, respectively, through macrophage polarization." (PMID 38983267, 2024). "SLIT2 suppresses, whereas ROBO1 promotes, SCLC growth by regulating the Tgf‐β1/glycogen synthase kinase‐3 beta (GSK3)/β‐catenin signaling pathway in tumor cells and TAMs." (PMID 35838343, 2023). "We then performed IHC-P staining of ROBO1 in 35 PDAC liver metastasis tissues and their matched primary tumours." (PMID 36792623, 2023). "Analysis of human samples showed reduced levels of Slit2 and increased levels of Robo1 in SCLC tumors, confirming the tumor‐suppressive function of Slit2 and the oncogenic role of Robo1 observed in our in vitro and in vivo studies." (PMID 35838343, 2023). "When ROBO1 is silenced, HCC cell proliferation, migration, invasion, tumor progression, and metastasis are confined." (PMID 37059586, 2023). "These opposite patterns of ROBO1 implicate a pro-tumorigenic role in HCC and a tumor-suppressive function in CCA." (PMID 37238655, 2023).
tumor (continued). "The reduced Robo1 is involved in the inactivation of PI3K/AKT/mTOR axis, leading to an impeded HCC cell proliferation, migration, and invasion in vitro and HCC tumor growth and metastasis in vivo." (PMID 33803804, 2021). "In order to assess the possible role of each drug on brain metastasis, eight protein/gene effectors known to have a more important role in brain metastasis than in primary tumours were considered: FGFR1; Ki-67, ROBO1; S100A7; S100B; SIRT1; SLIT2; and VEGFA." (PMID 33659043, 2021). "ROBO1 and ROBO2, crucial regulators of axon guidance, are considered potential tumor suppressor genes." (PMID 34642262, 2021). "ROBO1, a member of the roundabout (ROBO) immunoglobulin superfamily of protein, plays a role in cell migration and acts as a tumor suppressor gene." (PMID 33540941, 2021). "Specific blockage of Slit2 binding to Robo1 inactivated TGF-β/Smads signaling and inhibited tumor cell migration and metastasis, which can be partially restored by treatment with TGF-β1." (PMID 31242633, 2019). "The blocking of Slit2/Robo1 signaling by R5 attenuated TGF-β1 phosphorylation of Smad2 and Smad3 in Lovo cells, SW480 cells, and tumor tissues of ApcMin+ mice compared with mIgG-treated groups." (PMID 31242633, 2019). "Consistently, tumor growth was suppressed in ROBO1 expressing HCC1937 xenografts, while enhanced in ROBO1‐depleted MDA‐MB‐231 xenografts cotransplanted with SLIT2 expressing 199Ct fibroblasts." (PMID 29280568, 2018). "Further disruption of SLIT2 and ROBO1 has been shown to induce SDF1 and CXCR4 shifting the tumor microenvironment in an increased inflammatory state and further promoting invasion." (PMID 28440283, 2017). "After adjusting for multiple clinical covariates, SNPs on the LPHN2, ROBO1, SNTG1, and GRIK1 genes were significant independent predictors of poor tumor response (tumor growth) despite paclitaxel treatment." (PMID 29290962, 2017). "Furtherly, we predicited miR-218, one of the validated post-transcriptional tumor suppressors in a serie of tumors including HCC, as a potential regulator of ROBO1." (PMID 28977866, 2017). "Similar profile is seen in genes expressed in HCCN vs. HCV+HCC (tumor state): PCNA-AS1, ROBO1, DAB2, and IFI30 (lower part)." (PMID 28938650, 2017). "miR-218 is a post-transcriptional regulator of the receptor Roundabout1 (Robo1) and acts via inhibiting the SLIT-Robo1-mediated tumor migration, invasion in different cancer entities." (PMID 27462788, 2016). "Correlation analysis further revealed the loss of miR-218 was negatively correlated with up-regulation of ROBO1 in ESCC tissues and paired non-tumor tissues." (PMID 26610476, 2015). "Further analysis of the tumor tissues from the ApcMin/+;Slit2 mice and DMH/DSS-Slit2 mice revealed that activation of Slit2/Robo1 signaling led to an increased pSrc (Tyr 416) in these tumor tissues compared with their respective controls." (PMID 25605242, 2015). "We further investigated the correlation between miR-218 and ROBO1 in 97 pairs of ESCC tumor tissues and non-tumor tissues using quantitative RT-PCR." (PMID 26610476, 2015). "Our results revealed that ROBO1 and ROBO2 should be considered as tumour-suppressor genes in MDS and AML." (PMID 26608094, 2015). "Based on the present findings, we proposed that ROBO1 and ROBO2 should be considered as tumour-suppressor genes in MDS and AML." (PMID 26608094, 2015). "The characteristics of ROBO1 and ROBO2 as tumour-suppressor genes were also observed in the clinical results." (PMID 26608094, 2015). "In the network, Slit2 and Slit3 were redundantly activating Robo1, Robo2, Robo4 and ITGA1 receptors in tumor." (PMID 24597571, 2014). "While ROBO1 is expressed in both endothelial cells and other cell types, ROBO4 is expressed specially in vascular endothelial cells including the tumor vasculature." (PMID 24689049, 2014).
tumor (continued). "To explore the relationship between promoter methylation and gene expression in primary tumours we performed a qRT-PCR analysis of SOX9, HOXA9, AHR, ROBO1, and NR2F2 in a series of 36 MCL." (PMID 21603610, 2011). "In summary, our experimental results suggest that significant upregulation of the Robo1 gene in response to removal of miR-218 may induce a subsequent upregulation of the Slit-Robo1 pathway through its interaction with Slit2, facilitating tumor cell migration and invasion." (PMID 20300657, 2010). "We also provide quantitative evidence for potential use of ROBO1, ROBO4 and SLIT2 for prediction of tumor stage and differentiation status." (PMID 19114000, 2008). "We also observed that ROBO1 and SLIT2 differentiated histopathological subgroups of liver tissues depending on both tumor staging and differentiation status." (PMID 19114000, 2008). "Conversely, TQ treatment resulted in the downregulation of several genes overexpressed in GBM cells, including potential oncogenes like AEBP1, MIAT, GHR, LMO1, ELF3, and genes involved in tumor proliferation and migration such as EPHA4, COL3A1, PCDH10, ROBO1, ADAMTS5, PCDH18, ST8SIA1." (PMID 39874307, 2025). "However, the introduction of ROBO1-CAR significantly enhanced the recognition and engagement of NK cells with tumor cells." (PMID 39069888, 2024). "Importantly, ROBO1 and SLIT2 jointly promote RGC axon growth and play roles in neuronal axon guidance, angiogenesis, inflammatory cell chemotaxis, and tumor cell migration and transfer." (PMID 39574940, 2024). "Based on these results, we propose that Slit2 directly binds to Robo1 and acts as an important tumor‐suppressor, however, in the absence of Slit2, Robo1 promotes SCLC tumorigenesis in a ligand‐independent manner." (PMID 35838343, 2023). "The differential gene expression levels between the tumor and adjacent tissue indicated that the ROBO1, KLK6, LIMK2, KLK7, NLGN4X, MBP, and NEDD9 gene expression levels were higher in normal tissues than in tumors; however, EFNA1 was higher in the tumor than the normal ones." (PMID 38137332, 2023). "After we confirm the expression and distribution of SLIT2 and ROBO1 in samples from PDAC patients and several mouse models, we discover that SLIT2-ROBO1-mediated coadaptation facilitated the implantation and outgrowth of PDAC disseminated tumour cells (DTCs) in the liver." (PMID 36792623, 2023). "Further in vivo experiments illustrated that in the absence of SLIT2, ROBO1 significantly reduced the tumour burden induced by SW-1990 cells in subcutaneous PDAC xenograft mice." (PMID 36792623, 2023). "ROBO1, KLK6, LIMK2, KLK7, NLGN4X, MBP, and NEDD9 expression levels were significantly higher in normal tissues than in tumors, demonstrating the possibility of being a tumor suppressor gene." (PMID 38137332, 2023). "The results demonstrated that SLIT2 is derived from cancer-associated fibroblasts (CAFs) in patients and KPC mouse models but not from ROBO1+ tumour cells." (PMID 36792623, 2023). "Application of the 90Y-anti-ROBO1 Mab on HCC xenograft tumors in nude mice significantly suppresses tumor growth without necrosis or fibrosis." (PMID 37238655, 2023). "In addition, we also analyzed tumor angiogenesis genes, and the results showed that seven tumor angiogenesis genes (HIF1A, PDGFB, NRP1, VEGFB, FGFR1, ROBO1, and SLIT1) had substantially higher expression in the high-risk group compared with the low-risk group." (PMID 35311113, 2022). "ROBO1 protein expression was significantly correlated with patient’s gender (p = 0.006) and marginally significantly correlated with serum CA199 (p = 0.087), tumor location (p = 0.068), T stage (p = 0.069), and clinical stage (p = 0.061)." (PMID 35615148, 2022). "Having demonstrated that exosomal miR-29b from PC cells downregulated ROBO1 and SRGAP2 expression in HUVECs, we investigated whether ROBO1 and SRGAP2 were necessary for suppression of tumor cell-induced angiogenesis by exosomal miR-29b." (PMID 36277474, 2022).
tumor (continued). "Downregulated Robo1 by lentivirus-based miR-29a overexpression is involved in the inactivation of PI3K/AKT/mTOR axis, leading to impeded HCC cell proliferation, migration, and invasion in vitro and alleviated HCC tumor growth and metastasis in vivo." (PMID 33803804, 2021). "ROBO1 and ROBO4 were found to express in the vascular endothelial cells and may have some role in tumour angiogenesis, but very little is known to date." (PMID 33318575, 2020). "We show that SLIT2, in a ROBO1-dependent manner, negatively impacts the survival of KRAS-transformed cancer cells by inhibiting macropinocytosis, thus limiting protein uptake in a Glut-deprived state similar to the tumor microenvironment found in vivo." (PMID 32807784, 2020). "Pathway analysis suggests that miR-217 could be a potential oncogenic miRNA that negatively regulates the SIRT1, SMAD7, ROBO1, and FOXO3 genes, which are involved in tumor progression by diverse mechanisms." (PMID 30195786, 2018). "After adjusting for hormonal exposure and status, disease stage, and molecular subtype, in our sample, SNPs on the ADRGL2 ( p = 0.005), ROBO1 ( p = 0.047), SNTG1 ( p = 0.040), and GRIK1 ( p = 0.006) genes are significant independent predictors of tumor response to paclitaxel treatment." (PMID 29290962, 2017). "In vitro studies has shown that ROBO1 and ROBO2 function as tumour-suppressor genes." (PMID 26608094, 2015). "Moreover, Fisher's pairwise comparison analyses revealed that ROBO1, SLIT2 and ROBO4 significantly discriminated between different histopathological subgroups both in terms of differentiation status and/or tumor staging." (PMID 19114000, 2008). "Interestingly, tumour cells expressing Robo1-FL exhibited apoptosis when SLIT2 was lacking in the microenvironment." (PMID 36792623, 2023). "However, in some cases, SNVs were seen only in the tumor and not in the corresponding CSF cfDNA, including SNVs in ROBO1, APC, PIK3CA or ARID1A." (PMID 37444642, 2023). "This implies that TGF-β/Smads may not be the only signaling pathway that is involved in Slit2/Robo1-mediated tumor metastasis in CRC." (PMID 31242633, 2019). "Moreover, we found that ROBO1 is also highly expressed by stromal cells in these tumour samples, while ROBO2 is absent or expressed at very low levels in stromal cells." (PMID 30504844, 2018). "Thus, ROBO1 and ROBO2 may be considered to be tumour-suppressor genes in cancers, a notion that is also supported by our SNV and SNP data in lower and higher risk cases with MDS." (PMID 26608094, 2015). "Furthermore, knockdown of endogenous ROBO1 or specific blockade of SLIT2 binding to ROBO1 prevented E-cadherin degradation and reversed EMT (epithelium mesenchymal transition), resulting in diminished tumor growth and liver metastasis." (PMID 26674478, 2015). "In contrast, ROBO1 disconnects N-cadherin from the cytoskeleton in invasive cells, thus increasing their motility; c-MYB induces expression of MGMT, resulting in higher chemoresistance; expression of SOX2 and OLIG2 result in greater stemness and higher capacity for tumour formation." (PMID 23818228, 2013). "In addition, inhibition of Robo1 signaling by monoclonal antiserum inhibited tumor cell migration without affecting Abl kinase activity." (PMID 21301049, 2010). "We also noticed that induction of expression of Robo1 by the Robo1 mutant construct without the miR-218 binding site could reverse miR-218-mediated suppression of tumor cell invasion." (PMID 20300657, 2010). "To examine whether the expression and activation of Slit2 and Robo1 are correlated with intestinal tumorigenesis, we first analyzed the protein expression of Slit2 and Robo1 in the tumor tissues relative to their matched surrounding non-cancerous colonic tissues by immunohistochemical analysis." (PMID 25605242, 2015). "This could be because Robo1 is not the only target of miR-218 that is relevant to tumor metastasis." (PMID 20300657, 2010).
tumor (continued). "Surprisingly, we clarified that tumor metastasis, but not tumor growth of CRC is dependent on Slit2/Robo1 signaling induced activation of the TGF-β/Smads pathway." (PMID 31242633, 2019).
cancer (93 papers, 2004 to 2025). A tumor composed of atypical neoplastic, often pleomorphic cells that invade other tissues. "The absence of this modification increases ribosome frameshifts, affecting protein translation of key cancer-related proteins such as roundabout guidance receptor 1 (ROBO1), the loss of which inhibits cellular migration and EMT." (PMID 38476632, 2024). "Expression of SLIT2 or ROBO1 is frequently decreased in different types of cancer, due to promoter hypermethylation or loss of heterozygosity." (PMID 36942388, 2023). "In striking concordance with our results using ROBO1 siRNA in HeLa cells, the inactivating mutations resulted in hyperactivation of mTORC1 signaling in cancer cells." (PMID 37311584, 2023). "P16422|EPCAM and Q95604|1C17 from HCT116-specific group and Q9Y6N7|ROBO1 from DKO1-specific group are also high pathogenic cancer drivers (cancer driver score = 3)." (PMID 36639722, 2023). "All cancer-associated missense variants of ROBO1/4 and SLIT2 from COSMIC were screened for their pathogenicity." (PMID 33318575, 2020). "Among the possible candidates, we further analyzed DNMT1, CCKBR, WNT10B, NOG and ROBO1, which are five genes whose functions have been associated with carcinogenesis or cancer development." (PMID 21205300, 2011). "The findings presented herein reveal the associations between CAFs and cancer cells through SLIT2/ROBO1 and inflammatory signaling, and the key molecules involved may serve as potential biomarkers and therapeutic targets for GC." (PMID 37443302, 2023). "However, ROBO1 gene expression is fairly ubiquitous across multiple human tissues, and ROBO1 is frequently mutated across almost all cancer types, including breast and colon." (PMID 29698419, 2018). "Thus, the loss of the multifaceted cancer gene ROBO1 on TYW2 epigenetic inactivation provides an illustrative example of how alterations of tRNA chemical modifications might contribute to tumorigenesis." (PMID 32778592, 2020). "In contrast, GPC3 and ROBO1 were mainly expressed in the cytoplasm of cancer cells, although some expression patterns on the cell membrane of cancer cells were observed." (PMID 40076777, 2025). "CLDN1, EphB4, LAT1, HSP105α, and ROBO1 expression slightly decreased or remained unchanged but remained consistently high across both cancer types." (PMID 40806530, 2025). "ROBO1 has previously been shown to be related to cancer cell proliferation, migration, apoptosis, and angiogenesis." (PMID 40429844, 2025). "In HCC, ESCC, PDAC and GC, the Robo1 signaling axis activation can promotes cancer progression, and metastasis." (PMID 38081962, 2024). "CAR-NK immunotherapy shows great promise in cancer treatment, with roundabout guidance receptor 1 (ROBO-1) being another target of interest." (PMID 38801637, 2024). "Among these, Robo1 has been extensively investigated and established as a cancer promoter in various malignancies." (PMID 38081962, 2024). "The miR-152-3p/ROBO1 signaling axis promotes cancer progression and offers a potential immunotherapeutic target for HCC." (PMID 37238655, 2023). "Two different scFv antibody fragments that bind different domains of a cancer-related antigen, roundabout homolog 1 (Robo1), were fused to SpyTag and SpyCatcher at C-terminus." (PMID 36770585, 2023). "Numerous studies also implicate that hyper-methylation (epigenetic inactivation) of the promoters for SLIT1-3 and ROBO1-4 occur in various cancer types." (PMID 37238655, 2023). "We further show that attenuation of auto/para-crine SLIT2/ROBO1 signaling in cancer cells results in hyperactivation of mTORC1 and diminished autophagic flux." (PMID 37311584, 2023).